TLR7 (toll like receptor 7)
Diseases named in the same sentence as TLR7 in open-access papers (continued):
Sharing a sentence is not in itself a finding about the gene and the disease.
cancer (224 papers, 2007 to 2026). A tumor composed of atypical neoplastic, often pleomorphic cells that invade other tissues. "Mined by the ESTIMATE algorithm, the expression of TLR7 was also closely linked to various immune infiltration patterns in pan-cancer, and TLR7 was mainly enriched in macrophages, as revealed by single-cell RNA sequencing." (PMID 37362864, 2023). "TLR-7 polymorphisms have been investigated in cancer immunotherapy due to the ability of this PRR to induce a robust release of anti-cancer cytokines such as IL-12." (PMID 36432658, 2022). "TLR7 expression was found to be a significant risk factor for six different forms of cancer: BLCA (HR = 1.33, p < .05), KIRC (HR = 1.66, p < .01), LGG (HR = 2.17, p < .001), KIRP (HR = 2.52, p < .01), and THYM (HR = 3.23, p < .05)." (PMID 35801728, 2022). "Meta-analyses suggest that high expression of TLR4 or TLR7 may be associated with poorer survival across multiple cancers." (PMID 41228373, 2025). "Also, we tested the compound in a comprehensive cancer cell line panel, which includes TLR7 mutations among other common cancer mutated genes, to observe the possible TLR7-mediated anti-cancer effect of this compound." (PMID 29462934, 2018). "In accordance with our hypothesis, the Cancer Genomics database shows that TLR7 mRNA expression levels are associated with better overall survival of NSCLC patients, assessed as progression free status, disease free status, and disease-specific survival status." (PMID 33578955, 2021). "Guanosine analogs have immuno-stimulatory properties via the activation of TLR7, and guanosine-analog TLR7 agonists have been evaluated as a form of cancer immunotherapy." (PMID 40519286, 2025). "Although MDSCs suppress the immune system, TLR7 agonists can differentiate them into macrophages and dendritic cells, improving cancer immunotherapy." (PMID 39857735, 2025). "This review highlights the mechanisms of action, therapeutic potential, and recent progress in the development of TLR7/8 agonist-based strategies for cancer treatment." (PMID 41228373, 2025). "Transcriptional activation of a HERV-H provirus integrated downstream of the tandem TLR7 and TLR8 loci on human chromosome X initiates antisense transcription that is associated with loss of TLR7 and TLR8 transcription in several cancer types." (PMID 40773553, 2025). "TLR7/8 agonists have emerged as promising candidates in cancer immunotherapy due to their ability to activate innate immunity and stimulate robust antitumor responses." (PMID 41228373, 2025). "This review provides a comprehensive overview of TLR7/8 agonist-based strategies in cancer immunotherapy." (PMID 41228373, 2025). "The main factor in cancer survival was TLR7, with T and N stage next, and gender, stage, and smoking status were the least important." (PMID 39857735, 2025). "TLR7 affects cellular activity by modulating transcription and translation processes in cancer cells and immune cells." (PMID 41007327, 2025). "Keywords used in the search included: TLR7 agonist, TLR8 agonist, TLR7/8 agonist, TLR7/8-based cancer vaccine, TLR7/8-based cancer immunotherapy, TLR7/8-based combination treatment, and TLR7/8-based clinical trials." (PMID 41228373, 2025). "Together, these studies highlight the translational potential of TLR7/8 agonists in cancer vaccine development." (PMID 41228373, 2025). "TLR7 agonists are promising immunostimulatory agents for the treatment of chronic infections and cancer." (PMID 41217828, 2025). "The TLR7 agonist Imiquimod inhibits HCC by suppressing the self-renewal of cancer stem cells through the TLR7-IKK-NF-κB-IL6 signaling pathway." (PMID 40438106, 2025). "TLR7/8 agonists are also being used in cancer vaccines, which train the body to fight cancer more precisely." (PMID 41228373, 2025).
cancer (continued). "Modulation of the immune system has emerged as a key strategy in novel cancer therapies, demonstrating potential across various cancer types, including the recent exploitation ofTLR‐like receptors (TLR7, TLR8) and STING." (PMID 40606778, 2025). "This comprehensive review employed a strategic literature search to ensure broad coverage of studies investigating TLR7/8 agonist-based cancer vaccines and combination therapies." (PMID 41228373, 2025). "Targeting Toll-like receptors 7 and 8 (TLR7/8) has emerged as a promising strategy in cancer immunotherapy." (PMID 41228373, 2025). "Studies were included if they provided preclinical or clinical insights into the immunomodulatory agents, mechanisms of action, delivery strategies, or therapeutic efficacy of TLR7/8 agonists in cancer vaccination or combination approaches." (PMID 41228373, 2025). "We chose a potent TLR7/8 agonist R848 as a model drug due to its considerable potential for cancer treatment." (PMID 40592827, 2025). "Our study underlines the synergism between oxaliplatin ICD-inducing chemotherapy and imidazoquinoline TLR7 agonist-mediated innate immune activation in cancer therapy." (PMID 40230629, 2025). "Many TLR7/8 agonists combined with nanoparticles have been studied in cancer immunotherapy and photothermal therapy." (PMID 38605368, 2024). "Rsiquimod (R848), a toll-like receptor 7 (TLR7) agonist, has been demonstrated with potent anti-cancer effects in different animal models of cancer." (PMID 39449815, 2024). "It was shown that the expression of TLR-2, TLR-4, and TLR-7 mRNA and their protein levels were significantly higher in cancer tissues compared to control tissues (p < 0.05)." (PMID 39451226, 2024). "While TLR 7/8 agonist seems to boost the antitumor effect of different treatments, according to a meta-analysis, high TLR7 expression in tumors seems to lead to worse survival in a number of cancers." (PMID 38709790, 2024). "Based on these observations, TLR7 agonists considered to become a therapy weaponize the immune system against cancer." (PMID 39054418, 2024). "In the present study, we aim to develop a liposomal formulation that can co-deliver pTRAIL and the TLR7 agonist R848 to simultaneously induce cancer cell death and stimulate the immune microenvironment in an animal model of colorectal tumors." (PMID 39449815, 2024). "Researchers have recently found that the TLR7 and TLR8 genes and proteins are highly upregulated in CRC and are closely associated with cancer cells, but are rarely identified in leukocytes that have infiltrated stromal tumors." (PMID 38685971, 2024). "For instance, the use of cyclodextrin nanoparticles containing the Toll-like receptor 7/8 (TLR7/8) agonist R848 has demonstrated improved outcomes in cancer immunotherapy." (PMID 38543101, 2024). "Their experiments validated these effects in various tumor models, demonstrating the potential of TLR7/8 as effective vaccine adjuvants for cancer immunotherapy." (PMID 39206192, 2024). "Although TLR7 was also widely expressed in other cell types, including T cells, dendritic cells, and a fraction of cancer cells, the only cells that expressed both FRβ and TLR7 resided in the subset of myeloid cells." (PMID 38384467, 2024). "For example, TLR3 and TLR7 agonists activated NF-κB and triggered secretion of immune-stimulatory cytokines in macrophages and have been in clinical trials for cancer therapy." (PMID 38646639, 2024). "As one of the synthetic toll-like receptor (TLR) activators, imidazoquinoline R848 is an immunoadjuvant TLR7/8 agonist gaining attention in cancer immunotherapy." (PMID 39204409, 2024). "To achieve drug synergy, we developed a homologous cancer cell membrane vesicle (CM)-coated metal-organic framework (MOF) nanodelivery platform for the codelivery of a TLR7/8 agonist with an epigenetic inhibitor." (PMID 38811964, 2024).
cancer (continued). "3M-052 (a TLR7/8 agonist) is an 18-C fatty acyl chain that contains the hydrophobic imidazole quinoline and can be embedded in the lipid bilayer of cancer cell membrane vesicles through the lipid tail of 18 carbons." (PMID 38811964, 2024). "Single-stranded RNA has inherent adjuvant function stimulated by TLR7 and TLR8, and its relative ease in encoding multiple vaccine epitopes on the same RNA molecule indicates its advantages as a cancer vaccine formulation." (PMID 39136021, 2024). "Imiquimod and resiquimod (R848), an imidazoquinolin-like molecule that binds to TLR7/8, has shown promise as an immunomodulator for skin pathologies and cancers." (PMID 37766179, 2023). "Next, univariate Cox regression was used to examine the relationship between TLR7 expression and cancer prognosis." (PMID 37362864, 2023). "IMQ activates toll like receptor 7 (TLR7), which is overexpressed in different types of cancer, it also has potent antiviral and antitumour effects as shown in preclinical and clinical studies." (PMID 38077402, 2023). "We found TLR7 mRNA expression was significantly up-regulated in 6 cancer types and down-regulated in 6 cancer types, further validated in the HPA database at the protein level." (PMID 37362864, 2023). "This study highlighted TLR7’s multifaceted role in pan-cancer and provided new insights into TLR7’s potential role in drug regulation." (PMID 37362864, 2023). "The potential of combining TLR7/8 agonists with both current and novel antigens will be crucial adjuvant development for vaccines against cancer, infectious diseases, and allergic and autoimmune disorders." (PMID 38006036, 2023). "Emerging evidence has identified innate immune checkpoints and pattern recognition receptors, such as CD47 and Toll-like receptor 7 (TLR7), as promising therapeutic targets for cancer treatment." (PMID 37049910, 2023). "Nevertheless, in the context of cancer, pDCs demonstrate a diminished responsiveness to Toll-like receptor 7 and 9 (TLR7/9) activation, resulting in a marked reduction or outright loss of IFN-α production." (PMID 37858131, 2023). "Resiquimod is a TLR7/8 agonist mainly applied as an adjuvant with immunomodulatory effect in the context of cancer therapy (e.g. metastatic lung cancer, colon cancer)." (PMID 37786827, 2023). "This contrasts with the studies detailed above, which showed immune-related mechanisms for TLR7/8 ligation in cancer." (PMID 37112730, 2023). "Due to their potent innate immunostimulatory properties, TLR7/8 agonists have shown impressive results as anti-cancer therapy when administered systematically." (PMID 37765155, 2023). "Correlative studies conducted in cancer mouse models indicate that TLR7 agonist increases the ratio M1/M2 and dictates the improvement of the response to ICB." (PMID 37183363, 2023). "Subsequently, the peptide-decorated nanogels loaded with TLR7/8 agonist were successfully processed by antigen-presenting cells, enabling potent immune responses for future application in antigen-specific cancer immunotherapy." (PMID 37895096, 2023). "We used the GTEx database to determine the expression pattern of TLR7 in different organ tissues, and we used the CCLE database to determine the expression pattern of TLR7 in 21 different human cancer cell lines." (PMID 37362864, 2023). "Although it is the only approved TLR7 agonist in cancer therapy, imiquimod is allowed to be administered with topical formulation." (PMID 36793737, 2023). "TLR7 was significantly differentially expressed among normal tissues and different cancer cell lines." (PMID 37362864, 2023). "Since the activation of TLR7/8 triggers induction of a Th1-type innate immune response, their agonists have been suggested to be a promising strategy for cancer treatment." (PMID 37112730, 2023).
cancer (continued). "Imidazoquinolines (IMDs), such as resiquimod (R848), are of great interest as potential cancer immunotherapies because of their ability to activate Toll-like receptor 7 (TLR7) and/or TLR8 on innate immune cells." (PMID 37075115, 2023). "Despite these positive findings supporting the use of TLR7/8 agonist-based therapies in cancer, two studies showed opposing results." (PMID 37112730, 2023). "TLR7/8 agonists are cytokine inducers that can be used as cancer adjuvants to activate DCs and incite a robust T cell response." (PMID 35482149, 2022). "While many studies have been conducted on different TLR7/8 agonists, a breakthrough is urgently needed regarding the efficacy of cancer immunotherapy." (PMID 36476317, 2022). "We confirmed the expression of TLR9 and related endosomal protein TLR7 in the LM samples at protein and transcript levels on the tissues obtained from seven different cancer patients." (PMID 35697801, 2022). "In the present study, we describe the preclinical evaluation of TransCon TLR7/8 Agonist as an IT administered therapy for treating cancer." (PMID 36123697, 2022). "The anti-cancer activity of pDC can be triggered by engaging Toll-like receptor (TLR)-7 or TLR-9 with appropriate agonists such as IMQ/RSQ or unmethylated CpG-ODN, respectively." (PMID 36297510, 2022). "A recent study showed that imidazoquinoline-based TLR7/8 agonist can enhance the anti-cancer efficacy of monoclonal antibodies with improved ADCC in vitro and in vivo by inducing robust pro-inflammatory cytokine secretion and activating NK cells." (PMID 36476317, 2022). "Our laboratory has been committed to the development of TLR7 agonists to activate the innate immune system against cancer." (PMID 34975325, 2022). "These properties demonstrate how PLGA nanoparticles encapsulating TLR7/8 agonists can be used to improve cancer vaccines." (PMID 35482149, 2022). "A clinical trial to evaluate the safety and efficacy of TransCon TLR7/8 Agonist, as monotherapy and in combination with pembrolizumab, in cancer patients is currently ongoing (transcendIT-101; NCT04799054)." (PMID 36123697, 2022). "Urea-based Lys-Urea-Glu, which is a commonly used targeting moiety for prostate-specific membrane antigen (PSMA), serves as a model vector for cancer-targeted delivery of TLR7 agonists." (PMID 35806163, 2022). "Although the mechanism of action of TLR7/8 in cancer immunotherapy is still incomplete, TLRs on T cells are involved in the regulation of T cell function and serve as co-stimulatory molecules and activate T cell immunity." (PMID 36476317, 2022). "We believe that with the continuous progress of research, the new TLR7/8 targeted drugs will improve the treatment efficiency and survival rate of patients with malignant tumors and benefit more patients." (PMID 36476317, 2022). "So far, about 18 TLR7/8 agonists are used in clinical trials for the treatment of cancer and infections." (PMID 35292881, 2022). "Now, inspiredby the success of other TLR7 agonists in cancer immunotherapy, we evaluated the antitumor efficacy of the glyco-adjuvant." (PMID 36313164, 2022). "TLR7/8 agonist-loaded nanoparticles augment NK cell-mediated antibody-based cancer immunotherapy by promoting NK cell activation." (PMID 36476317, 2022). "Some microRNAs (miRNAs) bind as ligands to RNA-sensitive toll-like receptor 7 to regulate the inflammatory response, thereby contributing to the pathogenesis of cancer or neurodegeneration." (PMID 35637969, 2022). "Altogether, these data characterize TransCon TLR7/8 Agonist as a novel TLR therapy with the potential to provide clinical benefit to patients with cancer." (PMID 36123697, 2022). "The wide range of expression and clinical significance of TLR7/TLR8 in different kinds of cancers have been extensively explored." (PMID 36476317, 2022). "Small-molecular Toll-likereceptor 7/8 (TLR7/8) agonists hold promiseas immune modulators for a variety of immune therapeutic purposesincluding cancer therapy or vaccination." (PMID 34166595, 2021).
cancer (continued). "Oral delivery of synthetic TLR7/8 agonists has also been pursued for cancer treatments with the goal of increasing widespread use due to ease of administration and patient compliance." (PMID 34058283, 2021). "The role of TLR7 and its agonists in cancer insurgence and progression is currently still controversial and further investigation is required to shed light on TLR7 function in cancer pathogenesis." (PMID 34884547, 2021). "Agonists that activate TLR7/8 receptors are anattractive sourceof vaccine and cancer immunotherapy adjuvants." (PMID 34527180, 2021). "Considering the powerful immune regulatory function of TLR7, the agonists of TLR7 have been approved for topical application in cancer treatment." (PMID 34856991, 2021). "In a mouse model of lung adenocarcinoma, signal transduction by TLR7 on the surface of cancer cells can also recruit MDSCs to promote cancer progression and metastasis." (PMID 34689842, 2021). "Other failed attempts at parenteral delivery of TLR agonists for cancer therapy include research on loxoribine, a guanosine analog-based TLR7 agonist." (PMID 34058283, 2021). "Pan‐cancer analysis based on the TIMER database revealed a significantly different mRNA expression of TLR7 in many cancers, including STAD." (PMID 33982398, 2021). "Our data indicate that PRRs sustain a pro-resolving signaling in cancer cells that inhibits angiogenesis and identify TLR7 as crucial in this phenomenon in NSCLC cells." (PMID 33578955, 2021). "Several studies have reported that TLR7 combined with ICB has the potential to enhance the survival of many patients with cancer." (PMID 33982398, 2021). "Triggering TLR7 for cancer therapy with Imiquimod has already been approved by the FDA, and clinical trials with the TLR7/8 stimulating adjuvant R848 have been conducted." (PMID 34054859, 2021). "Similar to TLR3 and TLR7, TLR9 is expressed on endosomal membranes of several immune cells, and it has been linked to acute pancreatitis and cancer." (PMID 34884547, 2021). "NKTR-262 is another TLR7/8 agonist being evaluated in the context of intratumoral administration in advanced cancers in combination with the CD122 agonist NKTR-214." (PMID 34058283, 2021). "The small molecules Imiquimod (TLR7 agonist) and resiquimod (TLR7/8 agonist) are widely recognized topical drugs applied for benign and malignant epithelial tumors and cutaneous hematological malignancies." (PMID 34025657, 2021). "The results of the present study show that the RDgel can be used as an RNA adjuvant useful for cancer immunotherapy targeting TLR7/8." (PMID 32046113, 2020). "As effective agents to treat cancer and infectious diseases and to improve immune responses, agonists of TLR7 and TLR8 have attracted great attention." (PMID 33537035, 2020). "Different NP platforms such as micelles, liposomes, and polymeric NPs have been established in recent studies for TLR7/8 agonist-based cancer vaccine." (PMID 32850698, 2020). "Exosomal FMR1-AS1 helped maintain dynamic equilibrium in cancer stem-like cells through the TLR7/NFκB/c-Myc signaling pathway." (PMID 32597791, 2020). "Toll-like receptor (TLR) ligands are promising adjuvants for cancer immunotherapy, but TLR7/8 ligand Resiquimod has been shown to inhibit CD4 T-cell activation in a monocyte-dependent manner." (PMID 32183240, 2020). "In sum, the sex-dependent FMR1-AS1 within exosomes secreted by ESCC cancer stem-like cells can bind to endosomal TLR7 and activate TLR7-NFκB signaling, thus promoting the expression of downstream CSC-linked gene, c-Myc, in the recipient non-CSCs." (PMID 30736860, 2019). "Together, these results suggest that exosomal FMR1-AS1 induces ESCC cancer stem-like phenotypes by activating TLR7-NFκB signaling pathway, thus promoting c-Myc expression level." (PMID 30736860, 2019). "TLR7 is of special interest in cancer therapy on account of its strong stimulation of IL-12 and type-I interferons, which are important cytokines and effectors of T and NK cell functions." (PMID 31381571, 2019).